CCDC38 (coiled-coil domain containing 38)
Description:
Essential for male fertility. Required for sperm flagellum biogenesis. Also required for acrosome biogenesis. Required for the attachment of developing acrosomes to the nucleus during spermiogenesis and may be involved in the transport of fibrous sheath components.
Synonyms: FLJ40089
Tractability: No criterion of Open Targets' tractability assessment is met for any kind of drug.
Gene: Protein-coding gene on chromosome 12 (95,867,048 to 95,942,635, reverse strand). Ensembl gene ENSG00000165972.
Subcellular location: Cytoplasm, cytoskeleton, microtubule organizing center, centrosome; Cytoplasm, perinuclear region; Cell projection, cilium, flagellum; Cytoplasm, cytoskeleton
Gene Ontology:
Molecular function: ubiquitin-modified histone reader activity
Biological process: acrosome assembly; sperm flagellum assembly; chromatin organization
Cellular component: centrosome; cytoskeleton; motile cilium; perinuclear region of cytoplasm
Genetic constraint (gnomAD): Loss-of-function variants: 32 observed, 45.02 expected, observed/expected ratio (o/e) 0.71, 90% interval 0.54 to 0.95. The upper end of that interval is the gene's LOEUF score, 0.95, which puts it in group 4 of 6, group 1 being the genes least tolerant of losing a copy. Missense variants: 397 observed, 424.63 expected, observed/expected ratio (o/e) 0.93, 90% interval 0.86 to 1.02. Synonymous variants: 133 observed, 142.21 expected, observed/expected ratio (o/e) 0.94, 90% interval 0.81 to 1.08.
Homologues: Orthologues: chimpanzee CCDC38 (98% identical), macaque CCDC38 (93% identical), pig CCDC38 (76% identical), dog CCDC38 (75% identical), guinea pig CCDC38 (69% identical), rabbit CCDC38 (69% identical), rat Ccdc38 (69% identical), mouse Ccdc38 (60% identical). Paralogues in human: CFAP100 (31% identical), CFAP73 (10% identical), CCDC42 (9% identical).
Diseases named in the same sentence as CCDC38 in open-access papers:
CCDC38 is named in the same sentence as 2 diseases in open-access papers, as found by Europe PMC text mining. Sharing a sentence is not in itself a finding about the gene and the disease. The quoted sentences say what the papers report.
male infertility (1 paper, 2023). The inability of the male to effect fertilization of an ovum after a specified period of unprotected intercourse. "Knockout of Ccdc9, Ccdc38, Ccdc42, Ccdc62, Ccdc87 and Ccdc136 results in male infertility in mouse models because of defects in sperm flagella." (PMID 37601242, 2023).
CCDC38 also shares sentences with these, for which no sentence is quoted: cancer (1 paper).